PGR (progesterone receptor)
Diseases named in the same sentence as PGR in open-access papers (continued):
Sharing a sentence is not in itself a finding about the gene and the disease.
metastatic disease (29 papers, 2003 to 2025). "The incidence of de novo metastatic disease was significantly lower in the PgR-low group compared to the PgR-high group (47.8% vs. 61%; p = 0.019)." (PMID 40002286, 2025). "Long-term survivors in cases of metastatic BC in general are typically younger at the diagnosis of metastatic disease, are premenopausal and the most common biological subtype is estrogen receptor -positive, progesterone receptor-positive, and HER2-positive." (PMID 40627061, 2025). "The benefit is consistent, regardless of the number of prior treatments received, menopausal status, age, ductal or lobular histology, progesterone receptor status, and metastatic disease sites." (PMID 32882980, 2020). "Several previous studies demonstrated phenotypic discordances between primary and metastatic tumors in the standard-of-care biomarkers estrogen receptor (ER), progesterone receptor (PR), and HER2." (PMID 30665374, 2019). "Among them, HOXD10 and PGR are specific to primary tumor, while STAT3, JUN and JUNB are associated to metastatic tumor based on our integrative regulatory network and survival analysis." (PMID 28005952, 2016). "Studies have reported rates of 16–33.6% for estrogen receptor (ER), 32–40% for progesterone receptor (PR), and 10–15.7% for HER2 between primary and metastatic tumors." (PMID 41348261, 2025). "When revisiting the metastatic tumors stratified by APUC-6 levels, we found that tumors with high APUC-6 expression had increased expression of ESR1, ESR2, and PGR, but reduced expression of AR." (PMID 39207857, 2024). "The anatomopathological analysis confirmed ganglionar metastatic disease, compatible with breast origin with positive estrogen receptor (ER) and progesterone receptor (PR) and negative human epidermal growth factor receptor 2 (HER2)." (PMID 39944443, 2025). "Briefly, when analyzing the IHC characteristics, we observed that ER and/or PgR were more commonly expressed in patients with HER2 status discordance between the early and metastatic disease compared to patients with concordant HER2 status (p < 0.0001 and p = 0.006, for ER and PgR, respectively)." (PMID 34215766, 2021). "The assessment of estrogen and progesterone receptor status in the primary tumor may not reflect the status in the recurrent or metastatic tumor, and thus a biopsy of recurrent or metastatic carcinomas for hormone receptor analysis may be helpful." (PMID 36831434, 2023). "Also, there were no obvious PFS differences between the study arms in age, site of metastatic disease, histopathological classification, prior neoadjuvant or adjuvant CT, prior neoadjuvant or adjuvant ET, ECOG, progesterone receptor status, measurable disease, disease setting and DFI." (PMID 32497134, 2020). "Oestrogen receptor (ER) and progesterone receptor (PgR) status are widely used to select patients for adjuvant hormonal therapy and may predict response to cytotoxic chemotherapy in metastatic disease, but their role in predicting response to primary chemotherapy remains controversial." (PMID 15611798, 2005). "Additional immunostaining on the metastatic tumor was positive for GATA3, androgen receptor and estrogen receptor, but negative for progesterone receptor." (PMID 38831459, 2024).
Infertility (28 papers, 2010 to 2025). "Some of the sampled individuals had the G/A single nucleotide polymorphism at the +331G/A site in the PGR gene, only two of the infertile subjects (both of whom suffered from oligospermia) had the A/G genotype; all of the other subjects were G/G homozygous." (PMID 25653674, 2015). "Our results are not in agreement with previous reports of associations between progesterone receptor mutations and adverse reproductive outcomes including unexplained infertility, implantation failure after IVF/ET and unexplained RSA." (PMID 20090851, 2010). "Some authors suggested that lack of endometrial compaction may be due to the presence of progesterone receptor deficiency or endometrial resistance among some infertile women." (PMID 39685713, 2024). "Either a reduction in progesterone receptor expression or a downregulation of these receptors appears to be causing a delayed or reduced receptivity response which could feasibly cause infertility for this group of women." (PMID 36572790, 2023). "Mice with uterine deletion of Gpx4 by a progesterone receptor (Pgr)‐Cre driver (Gpx4f/fPgrCre) show embryo implantation failure resulting in complete infertility, despite normal uterine morphology and structure." (PMID 38044324, 2024). "Failure of progesterone to downregulate the progesterone receptor in uterine epithelia was correlated with aberrant αv- and β3-subunit expression and infertility." (PMID 37679778, 2023). "This role of PGR in heart development indicates that progesterone administration should be closely monitored in potential early-pregnancy patients undergoing infertility treatment." (PMID 36142249, 2022). "On the other hand, aberrant activation of the Notch1 pathway in the uterus leads to DNA hypermethylation of the progesterone receptor (PR) and thus compromises the P4 signaling and results in uterine developmental defects and infertility." (PMID 34460816, 2021). "The aim of this study was to assess the role of Ulipristal acetate (UPA), a selective progesterone receptor modulator, in restoring uterine cavity deformation due to submucous fibroids, in infertile patients attempting an IVF treatment." (PMID 32430027, 2020). "Uterine ablation of Foxo1 using the progesterone receptor Cre (PgrCre) mouse model resulted in infertility due to altered epithelial cell polarity and apoptosis, preventing the embryo from penetrating the luminal epithelium." (PMID 30452456, 2018). "As reported in previous literature, aberrant activation of canonical Notch1 signaling in the mouse uterus could decrease the level of progesterone receptor by hypermethylation that can lead to infertility." (PMID 36776897, 2023). "Possibly, new pharmacological approaches such as selective progesterone receptor modulators, AIs or GnRH antagonists may provide benefits in terms of reproductive outcomes in women with adenomyosis and infertility." (PMID 36552001, 2022). "For example, progesterone receptor knockout (PRKO) mice demonstrated that PR has essential roles in various aspects of reproductive capacity and that female mice are infertile due to a myriad of defects." (PMID 35563781, 2022). "It has also been revealed that the progesterone receptor (PR) and ER have a role in the pathophysiology of the MA and SCOS phenotypes in infertile males." (PMID 35455061, 2022). "Female mice with constitutive expression of PGR (Wnt7aCrePRALsL/+, i.e., PgrAOE/+) maintain epithelial expression of PGR-A across the WOR and exhibit infertility with defects in embryo attachment and stromal decidualization." (PMID 30452456, 2018). "Also, infertility has been observed in mice with ablation of SOX17 in progesterone receptor promoter (Pgr)-positive cells due to the lack of uterine glandular structures." (PMID 34768751, 2021).
Obesity (28 papers, 2008 to 2025). Accumulation of substantial excess body fat. "Published data show a clear association between obesity and BC, although it seems to be restricted to ER- and progesterone-receptor-positive BC." (PMID 32471192, 2020). "On the other hand, the association between obesity and progesterone receptor positive-tumours was strengthened." (PMID 19367278, 2009). "Progesterone receptor levels have also been linked to adipogenesis and obesity progression." (PMID 37628676, 2023). "Postmenopausal women with obesity are at a higher risk for a breast cancer diagnosis, particularly hormone receptor-positive breast cancers, which express estrogen receptor alpha (ERα) and progesterone receptor (PR)." (PMID 37296891, 2023). "Obesity in postmenopausal women is associated largely with estrogen receptor (ER)-positive and progesterone receptor (PR)-positive breast cancers, consistent with the major role played by estrogens synthesized by the stromal cells of adipose tissue in the pathogenesis of these tumors." (PMID 26516917, 2015). "Obesity is often related to an aberrantly high level of estrogen, estrogen receptor (ER), progesterone receptor (PR), or human epidermal growth factor receptor (HER2), which constitutes the predominant mechanism for the initiation and progression of BC." (PMID 33805515, 2021). "Subsequent experimental studies further support the close link between obesity and postmenopausal BC in mice, especially in the case of estrogen receptor positive (ER+) and progesterone receptor positive (PR+) tumors." (PMID 33572982, 2021). "All of the tested variables, i.e. overweight/obesity, stage, features of the primary tumor, estrogen and progesterone receptor expression, L1CAM expression, and adjuvant therapy, were associated with cancer-related mortality in unadjusted analyses." (PMID 33232359, 2020). "Nonetheless to respond the all the causes of dyslipidemia and obesity we are also investigating other SNPs that have been previously asssociated to this illness, like SNPs on genes such as CYP19A1, ESR2 and PGR." (PMID 28199328, 2017). "In addition, the effect of obesity on placental hormone production and myometrial progesterone receptor expression must be quantified in both animal models and women if we are to develop new approaches to modifying the deleterious effects of obesity." (PMID 26684329, 2015). "Furthermore, obesity combined with metabolic disorders and gut microbiota imbalance can lead to endometrial OS imbalance through downregulation of the oestrogen receptor (ER), which is important for the expression and activity of the progesterone receptor (PR)." (PMID 36766487, 2023). "In addition to lifestyle factors like obesity, breast cancer outcome is significantly affected by the non-modifiable characteristics of a given tumor, including tumor expression of estrogen receptor alpha (ERα), progesterone receptor (PR), and human epidermal growth factor receptor 2 (HER2)." (PMID 26709918, 2015). "Univariate analysis showed that the recurrence of EPs was not affected by age, obesity, EP size, EP position, estrogen receptor (ER) expression, or progesterone receptor (PR) expression." (PMID 38918774, 2024).
prostate carcinoma (24 papers, 2006 to 2024). A carcinoma that arises from epithelial cells of the prostate gland. "Dysregulated expression of PGR has been associated with cancer initiation and progression, such as hormone-dependent breast cancer, prostate cancer, and colorectal cancer." (PMID 38424455, 2024). "On the other hand, an association of PGR expression with aggressive phenotypes of prostate cancer was also reported." (PMID 28005952, 2016). "Earlier studies have implicated the androgen receptor (AR) in human prostate cancer cells and the progesterone receptor (PR) in breast cancer cells as stimulators of caveolin-1 expression." (PMID 20098621, 2010). "The bibliometric analysis aims to identify research trends in estrogen receptor (ERs) and progesterone receptor (PRs) in prostate cancer (PCa), and also discuss the hotspots and directions of this field." (PMID 37361598, 2023). "The FKBP52 cochaperone is a positive regulator of androgen (AR), glucocorticoid (GR), and progesterone receptor (PR) function and represents an attractive target for the treatment of castration-resistant prostate cancer." (PMID 36602710, 2023). "In prostate cancer tissues, an early study showed PGR expression in less than 50% of tumor cells, which was increased to over 60% in metastatic tissues." (PMID 34572596, 2021). "In this study, we conducted a comprehensive analysis of gene expression profiles for the classic PGR, and the membrane progesterone receptors in prostate cancers at the mRNA levels." (PMID 34572596, 2021). "In this study, we conducted a comprehensive gene expression analysis of seven progesterone receptor genes in primary and late-stage prostate cancer tissues." (PMID 34572596, 2021). "In this study, we conducted a comprehensive analysis of all progesterone receptor (PGR)-related genes in prostate cancer tissues and examined the correlations of their expression levels with disease progression and patient survival outcomes." (PMID 34572596, 2021). "Further analysis with more advanced technology is needed to delineate the exact expression pattern of the PGR gene in prostate cancers." (PMID 34572596, 2021). "We treated selected prostate cancer cell lines with the PGR/GR antagonist mifepristone to determine the ability of this drugs to inhibit the growth of prostate cancer cell lines." (PMID 33303959, 2020). "We thus tested the ability of the GR/PGR inhibitor mifepristone to inhibit the growth of prostate cancer cell lines compared to enzalutamide." (PMID 33303959, 2020). "Although less thoroughly investigated than the three receptors, ER, PgR, and AR, discussed here in detail, GR and MR certainly play roles in various cancers, including breast and possibly prostate cancers." (PMID 32718075, 2020). "Progesterone receptor positive stromal cells have been shown to inhibit prostate cancer cell migration and invasion." (PMID 32155897, 2020). "It would be of great interest to further assess the PGR isoform ratio in this prostate cancer cohort." (PMID 30054508, 2018). "Our survival analysis and the regulatory pairs with significant correlation values indicate that HOXD10 and PGR can be used as specific molecular signatures for the primary state in prostate cancer." (PMID 28005952, 2016). "The aim of this study was to evaluate the prognostic significance of progesterone receptor in tumor tissue of T1-3N0 prostate cancer patients undergoing prostatectomy." (PMID 25723513, 2015). "Other genes such as PGR and ER alpha were also studied because they have been identified in both normal and prostate cancer tissues." (PMID 25535400, 2014). "While discussion, here, centers on the use of these PET probes in breast and prostate cancers, in principle, they might also be useful in other types of cancers that are regulated by hormone action through ER, PgR, or AR." (PMID 32718075, 2020). "Besides, an increase of H3K27me3 marks on PGR gene can explain its downregulation in prostate cancer." (PMID 25535400, 2014).
prostate carcinoma (continued). "However, the role of PGR in the prostate cancer has not been fully understood yet." (PMID 28005952, 2016). "Based on the overall results, we believe in a direct role of EZH2 in silencing of RAR beta 2, ER alpha, PGR, and RGMA genes via H3K27me3 mark in prostate cancer and therefore indicates adverse prognosis." (PMID 25535400, 2014). "Contrary, RAR beta 2, ER alpha, PGR, and RGMA mRNA levels were decreased in prostate cancer tissue compared to normal one." (PMID 25535400, 2014). "In fact, to study histone methylation, a selection of six genes involved in prostate cancer was made, including RAR beta 2, ER alpha, PGR, RGMA, EZH2, and SRC3." (PMID 25535400, 2014). "The study demonstrated that H3K27me3 level was significantly enriched at the RAR beta 2, ER alpha, PGR, and RGMA promoter regions in prostate cancer tissues compared to normal tissues." (PMID 25535400, 2014). "The present study clearly pointed out H3K27me3 as an epigenetic mark involved in the silencing of RAR beta 2, ER alpha, PGR, and RGMA genes in prostate cancer." (PMID 25535400, 2014). "On the contrary, RAR beta 2, ER alpha, PGR, RGMA protein levels were notably reduced in prostate cancer tissues compared to normal tissues." (PMID 25535400, 2014). "In addition, we analyzed the expression levels of PGR, PGRMC1, and PGRMC2 genes in prostate cancers." (PMID 34572596, 2021). "Also the downregulation of SNAI2, ITGA3, BCL2, PGR, IGFPB3 and HOXD10 was previously reported for prostate cancer." (PMID 28005952, 2016). "High progesterone receptor density in tumor cells of the prostate cancer tumor is an independent negative prognostic factor for clinical failure." (PMID 25723513, 2015). "Also this study revealed that reverse correlation of RAR beta 2, ER alpha, PGR, and RGMA expressions with EZH2, SRC3, and AR expressions in prostate cancer tissues suggests that these genes are the target of EZH2." (PMID 25535400, 2014). "But currently, neither mutation nor structural alterations of these receptor genes in prostate cancer have been reported to be responsible for ER alpha or PGR down-regulation." (PMID 25535400, 2014). "Although PGR β-isoform protein (PR-B) exerted a higher expression level in prostate cancer tissues and was significantly correlated with a poor prognosis, PGR gene expression at the mRNA levels in prostate cancer tissues was not significantly different from normal prostate tissues." (PMID 34572596, 2021). "Meanwhile, PGR and PGRMC1 downregulation also had no significant impact on overall survival but a moderate impact on the progression-free interval in prostate cancers." (PMID 34572596, 2021).